RN7SL359P (RNA, 7SL, cytoplasmic 359, pseudogene)
Gene: Miscellaneous RNA gene on chromosome 2 (232,649,849 to 232,650,136, forward strand). Ensembl gene ENSG00000244384.
Homologues: Orthologues: chimpanzee Metazoa_SRP (99% identical), macaque Metazoa_SRP (95% identical), pig Metazoa_SRP (51% identical). Paralogues in human: RN7SL1 (79% identical), RN7SL2 (79% identical), RN7SL3 (79% identical), RN7SL44P (75% identical), RN7SL664P (75% identical), RN7SL408P (75% identical), RN7SL712P (75% identical), RN7SL769P (75% identical), RN7SL375P (74% identical), RN7SL45P (74% identical), RN7SL566P (74% identical), RN7SL7P (74% identical), and 704 more.